FGF1 (fibroblast growth factor 1)
Diseases named in the same sentence as FGF1 in open-access papers (continued):
Sharing a sentence is not in itself a finding about the gene and the disease.
Hepatic steatosis (11 papers, 2019 to 2026). Steatosis is a term used to denote lipid accumulation within hepatocytes. "hFGF1ΔHBS, a variant of human fibroblast growth factor 1 with three substitutions in its heparin-binding sites, was previously shown by our group to ameliorate fatty liver." (PMID 41827821, 2026). "Furthermore, FGF-1 has demonstrated its ability to improve DM-induced hepatic steatosis in leptin-deficient ob/ob mice through its anti-inflammatory function." (PMID 38542166, 2024). "Previously, we and others have shown that FGF1 effectively reduces hepatic steatosis in mouse models of MASLD." (PMID 41541501, 2026). "FGF1 signaling ties into a pathophysiological state of pre-existing chronic ER stress, ultimately clearing hepatic steatosis." (PMID 41541501, 2026). "Unexpectedly, administration of FGF-1 effectively reduced hepatocellular vacuolation and significantly improved hepatic steatosis in HFD-fed mice." (PMID 31866871, 2019). "We then assessed the effect of FGF-1 on HFD-induced hepatic steatosis." (PMID 31866871, 2019). "As FGF1 appears to specifically affect VLDL production rates without acutely modulating other major hepatic lipid fluxes, we postulate that FGF1 primarily regulates TG secretion, thereby clearing hepatic steatosis in obese mice." (PMID 41541501, 2026). "Peripheral injection of FGF1 in diabetic HFD-fed mice and ob/ob mice restored normoglycemia, improved insulin sensitivity, reduced hepatic steatosis and inflammation, independent of weight loss, and without inducing hypoglycemia." (PMID 41072794, 2025). "Together, our findings reveal a mechanism in which pharmacologically administered FGF1 acutely stimulates an adaptive UPR, leading to increased ER secretory capacity under pathophysiological (e.g. MASLD) conditions and a transient increase in VLDL secretion, ultimately clearing hepatic steatosis." (PMID 41541501, 2026).
lung fibrosis (11 papers, 2015 to 2025). "Similarly, elevated expression of FGF1/FGFRs in the pathogenic regions of IPF suggested that aberrant FGF1-FGFR signaling may contribute to the pathogenesis of lung fibrosis." (PMID 28974056, 2017). "Research has shown that high expression of FGF1 and its receptors (FGFRs) in the lungs of patients with idiopathic pulmonary fibrosis (IPF) activates the MAPK signaling pathway, promoting fibrosis." (PMID 39859240, 2025). "FGF1/FGFR is elevated in idiopathic pulmonary fibrosis (IPF), which is projected to lead to the pathogenesis of lung fibrosis." (PMID 41394119, 2025). "Until now, studies investigating the activity of heparin + FGF1 in the context of lung fibrosis have been carried out exclusively on cell lines." (PMID 26138239, 2015). "In patients with idiopathic pulmonary fibrosis, FGF1-FGFR signaling may contribute to the pathogenesis of lung fibrosis by supporting fibroblast migration and increased MAPK signaling." (PMID 38540252, 2024). "Importantly, activation of the downstream MAPK signaling pathway has been well documented to participate in the roles of FGF1 in wound healing in lung epithelium 16 vascular endothelial growth factor promotion 36, and idiopathic pulmonary fibrosis." (PMID 33994863, 2021). "Strong expression of FGF1/FGFRs in pathogenic regions of IPF suggest that aberrant FGF1-FGFR signaling is increased in IPF patients and may contribute to the pathogenesis of lung fibrosis by supporting fibroblast migration and increased MAPK-signaling." (PMID 26138239, 2015). "In the case of idiopathic pulmonary fibrosis, on the other hand, FGF1/FGFR signalling is aberrantly increased and may promote fibroblast migration via increased MAPK signalling, leading to the pathogenesis of lung fibrosis." (PMID 37240405, 2023). "Previous studies reported that some growth factors or proteins, like fibroblast growth factor-1 (FGF-1) or caveolin-1, could inhibit pulmonary fibrosis by regulating the degradation of TGF-βRI." (PMID 33808650, 2021). "Though IPF lung fibroblasts responded to heparin + FGF1 treatment by attenuating COL1a1 expression and increased apoptosis, increased p-ERK1/2 signaling along with enhanced cell migration was also observed reflecting a potentially dual nature of FGF1/FGFR in the context of lung fibrosis." (PMID 26138239, 2015).
myocardial infarction (11 papers, 2017 to 2025). Gross necrosis of the myocardium, as a result of interruption of the blood supply to the area, as in coronary thrombosis. "FGF1 coacervate inhibited ventricular dilation and preserved cardiac contractibility better than free FGF1 and saline control in a mouse model of acute myocardial infarction." (PMID 35433888, 2022). "FGF1 also displays favorable effects on maintaining myocardial integrity and preventing cardiac dysfunction in post-myocardial infarction." (PMID 35118146, 2021). "In myocardial infarction, FGF1 has been shown to regulate angiogenesis and induce cardiomyocyte regeneration and improves function recovery of the heart." (PMID 35011683, 2021). "It would be worthwhile to investigate the role of endogenous Fgf1 in cardiomyocyte mitosis and cell cycle reentry upon myocardial infarction in the future." (PMID 35011683, 2021). "In vivo, FGF1 has been shown to induce cardiomyocyte regeneration and improve cardiac function after myocardial infarction." (PMID 35011683, 2021). "After myocardial infarction in adult mice, combinatorial therapy with p38 inhibitor and FGF1 has been shown to induce cardiomyocyte proliferation and cardiac tissue regeneration, reduce scar formation and improve cardiac function." (PMID 34692797, 2021). "FGF1 can promote cardiac regeneration in a myocardial infarction rat model." (PMID 28629174, 2017). "Some highly potent proteins in MSC-derived exosomes have the potential to improve cardiac function after myocardial infarction (MI), including growth factors such as fibroblast growth factor 1 (FGF1) and neuregulin-1 (NRG1), involved in cardiac development and regeneration in an MI rat model." (PMID 33396739, 2020). "It was also reported that FGF1 and FGF2 expression was increased following myocardial infarction in rats." (PMID 31149027, 2019). "In addition, controlled delivery of FGF1 and neuregulin-1 (NRG1) from biodegradable microparticles could promote cardiac repair in a rat myocardial infarction model through induction of tissue revascularization and activation of endogenous regeneration." (PMID 32210827, 2020). "In particular FGF1, FGF2, and the herein not analysed FGF4 show promising results in clinical trials to improve angiogenesis after myocardial infarction or angina pectoris." (PMID 39940657, 2025).
atherosclerosis (10 papers, 2013 to 2026). A disease characterized by the build-up of fatty material and calcium deposition in the arterial wall resulting in partial or complete occlusion of the arterial lumen. "It has been reported that upregulation of FGF1 expression to be able to ameliorate atherosclerosis development." (PMID 36890543, 2023). "Zhang L, Cheng H, Yue Y, Li S, Zhang D, He R. TUG1 knockdown ameliorates atherosclerosis via up-regulating the expression of miR-133a target gene FGF1." (PMID 35703653, 2022). "In a PDGF-BB-stimulated atherosclerosis model, the researchers discovered that circLMF1 deficiency was found to suppress cell survival, cell cycle progression, and migration, possibly via the miR-125a-3p/VEGFA or FGF1 axis." (PMID 35607519, 2022). "In the PDGF-BB-stimulated atherosclerosis model, it was discovered that circLMF1 deficiency inhibited cell survival, cell cycle progression, and migration, possibly via the miR-125a-3p/VEGFA or FGF1 axis." (PMID 35607519, 2022). "Up-regulating FGF1 expression modulates to ameliorate atherosclerosis." (PMID 32985665, 2020). "Our study suggested that targeting TNK2‐AS1/miR‐150‐5p/VEGFA/FGF1 axis may be effective in attenuating atherosclerosis." (PMID 31468685, 2019). "A previous study showed TUG1 knockdown could ameliorate atherosclerosis via inducing FGF1 expression." (PMID 30873207, 2019). "As the role of FGF in atherosclerosis is much less documented than its role in restenosis, we checked the presence of FGF and its receptors in atherosclerotic lesions of apoE-deficient mice and found high expression of FGFR1 and the FGFR ligands FGF1 and FGF2." (PMID 24224032, 2013). "Despite the beneficial hepatic effect of FGF1, ApoB lipoprotein particles (especially LDL-cholesterol) are central to atherosclerosis development and even with effective LDL-cholesterol control, residual risk is prevalent in patients with metabolic syndrome." (PMID 41541501, 2026). "Although the presence of FGF1 and FGF2 as well as their receptors has been shown on atherosclerotic arteries of rat and human origin, only very few studies have addressed the role of these receptors during the early phases of atherosclerosis development." (PMID 24224032, 2013).
lung carcinoma (10 papers, 2010 to 2024). "We found that a short treatment with afatinib caused an acute upregulation of FGF1 in EGFR mutant lung cancer cells." (PMID 35840561, 2022). "In the previous work, we have shown that FGF1 can protect lung cancer (DMS114) and osteosarcoma (U2OSR1) cells, which overexpress FGFR1, from drugs targeting tubulin polymerization." (PMID 37509496, 2023). "IGF-1 and fibroblast growth factor -1 (FGF-1) can synergistically promote the expansion of lung cancer stem cells (LCSCs) and significantly down regulate the apoptotic signals through the activation of MAPK signaling pathway." (PMID 36329881, 2022). "To determine whether human FGFR1 will be activated in this mouse system we demonstrated, that murine FGFR1 ligands, such as FGF1 and FGF2 can activate human FGFR1 using the human H520 lung cancer cell line that overexpresses FGFR1." (PMID 27391347, 2016).
osteosarcoma (10 papers, 2012 to 2025). A usually aggressive malignant bone-forming mesenchymal neoplasm, predominantly affecting adolescents and young adults. "To verify the results obtained for NLS mutants, we also knocked-down LRRC59, a protein-mediating nuclear transport of FGF1, in the human osteosarcoma U2OSR1 cell line constitutively expressing FGFR1." (PMID 35159330, 2022). "In the next step we have examined the effect of selected antibody fragments on FGF1 trapping in human osteosarcoma G-292 cancer cell line." (PMID 30134556, 2018). "Expression of angiopoeitin 1 was generally higher in osteosarcoma xenografts than in most other pediatric solid tumors, whereas among the osteosarcoma xenografts FGF1 was expressed most highly in the OS-1 model." (PMID 22530037, 2012). "In our previous study, complement-activated supernatant from NS-treated osteosarcoma cell lines demonstrated enhancement of angiogenesis in HUVECs through increased growth factor production, such as vascular endothelial growth factor-A and fibroblast growth factor-1." (PMID 33805189, 2021). "We serum-starved U-2 OS (osteosarcoma) and BT20 (EGFR-amplified triple-negative breast cancer) cells and exposed them to various RTK ligands (EGF, FGF1, PDGF)." (PMID 40667115, 2025).
bladder cancer (9 papers, 2012 to 2024). "Thiery’s group found that fibroblast growth factor 1 (FGF1) induced an EMT effect in rat bladder carcinoma cells, linking EMT to cancer." (PMID 39164745, 2024). "Dysregulation of fibroblast growth factors, especially FGF1 and FGF3, have been associated with the risk of bladder cancer." (PMID 35888106, 2022). "Induction of EMT by FGF-1 treatment or Slug overexpression in the rat bladder carcinoma cell line NBT-II is also characterized by dissociation of desmosomes, with no change in E-cadherin expression." (PMID 22931165, 2012). "However, to the best of our knowledge, the role of FGF4 in bladder cancer is limited, despite its prominent role in MAPK pathway activation linked with FGF1 and FGF3." (PMID 35888106, 2022). "The role of FGF1 and FGF3 is evident in bladder cancer; however, the role of FGF4 is vague." (PMID 35888106, 2022). "A rat bladder carcinoma cell line, NBT-II, can undergo EMT following addition of several growth factors including FGF1, FGF7, and FGF10 and NBT-II carcinoma cell lines that were rendered autocrine for FGF1 activation had a much higher level of tumorigenicity." (PMID 22701738, 2012).
liver fibrosis (9 papers, 2007 to 2023). "In another study, liver fibrosis resulting from chronic exposure to CCl4 was markedly decreased in the liver of FGF1/FGF2-deficient mice." (PMID 31652997, 2019). "In another study, liver fibrosis resulting from chronic exposure to CCl4 was markedly decreased in liver of FGF1/FGF2-deficient mice." (PMID 31652997, 2019). "In another study, liver fibrosis resulting from chronic CCl4 exposure was markedly decreased in the livers of FGF1/FGF2-deficient mice." (PMID 24710173, 2014). "Liver fibrosis resulting from chronic carbon tetrachloride (CCl4) exposure has been shown to be markedly decreased in FGF1/FGF2-deficient mice." (PMID 24710173, 2014). "We speculated that endogenous FGF1 deficiency aggravated hepatic oxidative stress and cell death would also exacerbate DOX-induced liver fibrosis." (PMID 37999577, 2023). "FGF1 deletion impairs Nrf2-mediated antioxidant defensive responses, resulting in exacerbated hepatic oxidative stress, which in turn aggravates hepatic cell death and injury, eventually deteriorating hepatic fibrosis and accelerating the development of DOX-induced hepatoxicity." (PMID 37999577, 2023). "We showed that FGF1 treatment reduced plasma ALT levels, ameliorated liver lipid accumulation as well as hepatic apoptosis and liver fibrosis and corrected hepatic autophagy." (PMID 32194395, 2020). "The mice that lack FGF1 and FGF2, liver fibrosis was decreased." (PMID 31031647, 2019). "Indeed, the double knockout of FGF1 and FGF2 significantly decreases chemically induced liver fibrosis, while transgenic expression of FGF2 in cardiomyocytes exacerbated myocardial injury." (PMID 22606265, 2012).
Alzheimer disease (8 papers, 2005 to 2024). A progressive, neurodegenerative disease characterized by loss of function and death of nerve cells in several areas of the brain leading to loss of cognitive function such as memory and language. "Interestingly, FGF1 has been shown to protect neurons from excitotoxic stress, and low FGF1 mRNA levels have been implicated in Alzheimer's disease." (PMID 15960800, 2005). "Demographic and clinical data of patients with Alzheimer’s disease grouped based on APOE-ε4 carriers versus non-carriers or FGF1-rs34011-GG (GG-carriers) versus FGF1-rs34011-A-allele carriers (A-allele-carriers)." (PMID 31164996, 2019). "Lastly, the FGF1 levels in serum and CSF were significantly higher in Alzheimer’s disease patients." (PMID 28974056, 2017). "Although FGF1 may be involved in the pathophysiology of Alzheimer’s disease similar to FGF2, more studies need to be commenced to deduce the exact molecular signaling pathways." (PMID 28974056, 2017). "Previously FGF1 was reported in neurons and reactive astrocytes in Alzheimer’s disease." (PMID 25589163, 2014). "Although there remains a paucity of studies investigating the specific role of FGF-1 in the pathological mechanisms of cognitive impairment, several lines of evidence have shown that dysregulation of FGF-1 expression is closely associated with dementia, especially Alzheimer’s disease." (PMID 37214403, 2023).
cardiac hypertrophy (8 papers, 2013 to 2023). "The hierarchical cluster heatmap and Venn diagram indicated that 5 of 22 FGF genes (FGF1, FGF5, FGF12, FGF16, and FGF18) were associated with myocardial hypertrophy." (PMID 36871047, 2023). "As FGF1 improved mitochondrial oxidative phosphorylation, we explored the role of FGF1 in pathological cardiac remodelling using two independent cardiac hypertrophy models, TAC and Ang II." (PMID 34358309, 2022). "As it was revealed, FGF-1 can promote myocardial hypertrophy as a reparative response to myocardial damage in patients with idiopathic cardiomyopathy." (PMID 34204341, 2021). "Also, whole body knockout of miR-27b was found to attenuate pressure overload-induced cardiac hypertrophy via FGF1, but this could be due to extracardiac effects mediated by miR-27b-3p such as adipocyte browning." (PMID 37276142, 2023). "By targeting and downregulating fibroblast growth factor 1 (FGF1), a mitochondrial oxidative phosphorylation (OXPHOS) enhancer, miR-27b-3p aggravates pressure overload-induced cardiac hypertrophy in mice." (PMID 35681500, 2022). "The sets include functions such as PI3K and MAPK kinase signaling pathways, involved in HF-related cardiac hypertrophy, or fibrinolysis and coagulation processes (e.g. FGB, SERPINE1 or SERPING1) and growth factors (e.g. FGF1 or PDGF) related to MD induction." (PMID 32053711, 2020).
diabetic cardiomyopathy (8 papers, 2013 to 2024). Diabetic cardiomyopathy is a disorder of the heart muscle in people with diabetes. "Here, we show that serum levels of FGF1 were decreased and positively correlated with fraction shortening in diabetic cardiomyopathy (DCM) patients, indicating that FGF1 is a potential therapeutic target for DCM." (PMID 33762571, 2021). "This study aimed to evaluate the preventive effect of FGF1-loaded nanoliposomes (FGF1-nlip) combined with ultrasound-targeted microbubble destruction (UTMD) on diabetic cardiomyopathy (DCM) using ultrasound examination." (PMID 31998132, 2019). "Furthermore, FGF-1 ameliorates diabetic cardiomyopathy through the alleviation of oxidative stress and anti-apoptotic effects." (PMID 38542166, 2024). "FGF-1 was found to prevent diabetic cardiomyopathy by reducing oxidative stress in mouse hearts." (PMID 34281287, 2021). "FGF-1 could prevent diabetic cardiomyopathy in rats, mice, and H9C2 cardiomyocytes by attenuating high-glucose-induced cardiac hypertrophy, oxidative stress, and myocardial fibrosis." (PMID 34281287, 2021). "Acidic fibroblast growth factor (FGF1) has great potential in preventing diabetic cardiomyopathy." (PMID 31998132, 2019). "Consistent with our results, other studies have reported that FGF-1 significantly increases AMPK phosphorylation, preventing nonalcoholic fatty liver disease and diabetic cardiomyopathy in mice." (PMID 38542166, 2024).
gastric cancer (7 papers, 2014 to 2023). A primary or metastatic malignant neoplasm involving the stomach. "Additionally, miR-205-5p targets a plethora of communication factors, including, e.g., VEGF and FGF1 leading to reduced angiogenesis in gastric cancer, whereas exosomal miR-205-5p induces angiogenesis in nasopharyngeal carcinoma by targeting desmocollin-2." (PMID 38003618, 2023). "MiR-205-5p is downregulated in gastric cancer tissues, it suppresses proliferation and angiogenesis in gastric cancer by reducing the expression of VEGFA and FGF1." (PMID 34977016, 2021). "We focused on fibroblast growth factor 1 (FGF1) and its receptor (FGFR), a member of receptor tyrosine kinase family (RTKs), as its overexpression or aberrant activation has been reported in breast, lung, and gastric cancers." (PMID 30134556, 2018).
glioblastoma (7 papers, 2018 to 2025). The most malignant astrocytic tumor (WHO grade IV). "IKK16 also abrogates resistance of glioblastoma U87MG cells to the Gefitinib+PHA665752 (a MET inhibitor) treatment via blocking fibroblast growth factor 1 (FGF1) expression." (PMID 36358633, 2022). "HOTAIR depletion acts as an anti-cancer agent in glioblastoma, regulating the FGF1-dependent pathway through miR-326." (PMID 32283739, 2020). "HOTAIR and the HOTAIR/miR-326/FGF1 axis are a promising therapeutic strategy for glioblastoma therapy." (PMID 32283739, 2020). "In human glioblastoma cells, RFX1 downregulates fibroblast growth factor 1 expression." (PMID 37781522, 2023).